RNU6-696P (RNA, U6 small nuclear 696, pseudogene)
Gene: Small nuclear RNA gene on chromosome 21 (37,045,530 to 37,045,636, forward strand). Ensembl gene ENSG00000212136.
Homologues: Orthologues: chimpanzee U6 (100% identical), guinea pig U6 (76% identical), rat U6 (74% identical), dog U6 (70% identical), mouse Gm26008 (68% identical). Paralogues in human: RNU6-1060P (85% identical), RNU6-949P (85% identical), RNU6-1011P (84% identical), RNU6-242P (84% identical), RNU6-24P (84% identical), RNU6-262P (84% identical), RNU6-744P (84% identical), RNU6-1175P (83% identical), RNU6-11P (83% identical), RNU6-1309P (83% identical), RNU6-19P (83% identical), RNU6-37P (83% identical), and 1288 more.